GAPDH (glyceraldehyde-3-phosphate dehydrogenase)
Diseases named in the same sentence as GAPDH in open-access papers (continued):
Sharing a sentence is not in itself a finding about the gene and the disease.
cancer (continued). "The differential expression ratio (epithelial cell transforming sequence 2 oncogene—ECT2/ Glyceraldehyde 3-phosphate dehydrogenase—GAPDH) of ECT2 and the number of cancer cells was linearly correlated, as shown by the scatter plot used to confirm the RNA extraction quality (r = 0.97)." (PMID 28362321, 2017). "However, non-flux-controlling glycolytic steps such as glyceraldehyde-3-phosphate dehydrogenase (GAPDH), pyruvate kinase (PYK), and lactate dehydrogenase (LDH) have been also proposed as suitable targets for inhibition of cancer glycolysis." (PMID 27721794, 2016). "In the preceding section, we have shown that GAPDH can interact with GPI and PKM2 in cancer cells." (PMID 26911935, 2016). "The recognition of telomeric sequences by GAPDH is not specific to cancer but is also found in the Trypanosoma cruzi parasite." (PMID 26556350, 2015). "Taken together, cancer-associated up-regulation of the reference genes used in the present study was (i) definitely present (PGK1), (ii) vaguely present (GAPDH) or (ii) absent (ACTB)." (PMID 26468005, 2015). "Therefore, p-AKT enhances aerobic glycolysis rate in cancer cells because p-AKT can promote the expression of glycolytic enzymes, including GAPDH, via HIF-131." (PMID 25859407, 2015). "In fact, despite the lack of direct proofs of GAPDH involvement in DNA replication and cell proliferation, this enzyme is considered as a potential cancer therapeutic target." (PMID 26017754, 2015). "Glyceraldehyde-3-phosphate dehydrogenase (GAPDH), commonly used as a load control because of its stable level, has been reported to accumulate in mitochondria of some cancer cell lines upon induction of apoptosis, and to participate in release of pro-apoptotic proteins from mitochondria." (PMID 25326334, 2014). "Glucose transporters, or key enzymes as hexokinase II (HKII), glyceraldehyde-3-phosphate dehydrogenase (GAPDH), lactate dehydrogenase (LDH) and the isoform M2 of pyruvate kinase (PKM2) are upregulated in cancer cells and accordingly suggested as potential therapeutic targets." (PMID 23762063, 2013). "GAPDH and ACTB are most commonly used for normalization, including studies on cancer." (PMID 17640361, 2007). "However, no reduction in the ratio between mRNA sequences encoding human CXCR4 and GAPDH was observed in any treatment group suggesting that the absence of immobilised CXCL12 in heparin-treated animals did not select for non-CXCR4-expressing variants of the cancer." (PMID 17726466, 2007). "It was reported that GAPDH and ACTB were also differentially expressed in other cancer types." (PMID 17640361, 2007). "Likewise, a lack of stability in GAPDH levels between several human cancers and their respective control tissues was found in a Belgian study." (PMID 40943534, 2025). "Together with recent evidences showing that some key-glycolytic enzymes, such as GAPDH and PKM were able to regulate the translation of mRNAs in human T-cells and mouse embryonic stem cells, respectively, we explored the role of HK2 as an RBP regulating mRNA translation in human cancer cells." (PMID 40956859, 2025). "A TCGA RNA-Seq database pan-cancer study aiming to identify the best reference gene combinations in 12 cancer types found that one of the most frequently used HKGs, GAPDH, showed relatively low stability of mRNA levels and did not enter any recommended gene combination." (PMID 40943534, 2025). "Furthermore, GAPDH’s non-enzymatic functions are also critical in cancer progression by influencing diverse cellular processes beyond metabolism." (PMID 38611852, 2024). "Assuming that these increases may reflect the vigorous total exosome production from aggressive cancer cells as confirmed in previous studies, we adopted ACTB, which had a greater difference, as one of the candidate biomarker PEX mRNAs, and used GAPDH as the reference gene." (PMID 39867897, 2024). "ENO1, GAPDH, NQO1, PDIA4, and PDIA6 may serve as potential targets for cancer therapy." (PMID 37955007, 2023).
cancer (continued). "Since cancer cells display increased uptake of glucose and aerobic glycolysis (the Warburg effect) for their growth requirements, we analysed L-lactate secretion in PDAC cell medium after 48 h treatment with the GAPDH inhibitors AXP-3009, AXP-3018, and AXP-3019." (PMID 35804925, 2022). "It is intriguing to speculate that GAPDH’s putative function in binding AKT and vesicle trafficking might be related to the transport of metabolic proteins such as GLUT1 and GLUT4, but this function is uncharacterized in cancer cells." (PMID 36267982, 2022). "If GAPDH promotes apoptosis, then GAPDH inhibitors might suppress apoptosis in non-malignant cells while promoting cell death in cancer cells- a potential therapeutic window." (PMID 36267982, 2022). "The enzymes of glycolysis glyceraldehyde-3-phosphate dehydrogenase (GAPDH), enolase 1 (ENO1) and lactate dehydrogenase (LDHA) and glycerol-3-phosphate dehydrogenase (GPD1) which shuttles electrons to mitochondria, revealed a significant increase in carcinomas when compared to NAT." (PMID 35534478, 2022). "In carcinoma cells, lactate dehydrogenase isoform A (LDHA) preferentially converts synthetic pyruvate to L-lactate by removing hydrogen from the NADH molecule in the final step of the glycolytic pathway, thereby regenerating NAD+ to maintain glycolysis, which serves as a substrate for GAPDH." (PMID 36612084, 2022). "Therefore, GAPDH, GSTP1 and other proteins reported here may represent candidate targets to further enhance the potential for nitroimidazole-based cancer therapeutics." (PMID 33640700, 2021). "Altogether, the findings imply that MS13 may demonstrate its anti-cancer effects in U-87 MG and SH-SY5Y cells by downregulating GAPDH and ENO1, which disrupts the glycolytic pathway and subsequently results in the reduction of energy production and inhibition of cell proliferation." (PMID 33996900, 2021). "Similarly, two other genes, GAPDH and ENO1, promote cancer progression in GBM." (PMID 34831287, 2021). "Regulation of GAPDH expression in cancer cells is not obvious." (PMID 32252351, 2020). "The relatively oxidative environment of the HeLa cancer cell line may account for the high level of reversible cysteine modification of GAPDH even without diamide treatment." (PMID 32332101, 2020). "Interestingly, another well-known housekeeping gene ACTB was ranked 14 out of 20,501 genes, suggesting that both GAPDH and ACTB genes might be unsuitable housekeeping genes for gene expression experiments, particularly in cancer studies." (PMID 31324856, 2019). "We can not rule out the possibility of such modification in GAPDH by MG, which may inhibit its enzymatic activity in cancer cells." (PMID 26911935, 2016). "GAPDH is involved in functional networks that might be deregulated in cancer cells and is not suitable for studies in cancer cell lines." (PMID 27625650, 2016). "However, our analysis cannot exclude the possibility that the observed up-regulation of both GAPDH and GACC genes may be a secondary effect of the cancer that is attributable to the high-energy demands required for rapid growth." (PMID 23620736, 2013). "Treatment with nanoliposomal C6-ceramide did not decrease GAPDH protein expression in non-transformed cells from normal donors, which again alludes to the preferential specificity of nanoliposomal C6-ceramide treatment for cancer cells." (PMID 24367685, 2013). "To further explore the correlation of the up-regulation of GACC genes and that of the other GAPDH positively correlated genes in NSCLC, we speculated that cancer may arise in part from a reduction in the normal regulation of senescence by genes associated with the cell cycle." (PMID 23620736, 2013). "Since it has been established that GAPDH achieves its non-glycolytic functions through PTMs, compromising its glycolytic role conceivably, it would have serious consequences on the bioenergetics of cancer cells." (PMID 22964488, 2012).
cancer (continued). "However, the growth inhibitory activity of GAPDH against cancer cells has not been reported." (PMID 25785838, 2015). "We transfected the murine cancer cell line TC-1 with uORF-SIINFEKL reporters and the GAPDH negative control." (PMID 40866359, 2025). "Interestingly, the expression levels of GAPDH were downregulated in the NDV-treated cells more than in the 2-DG-treated cells at some time points tested in both cancer cell lines, this result suggests that NDV may play an important role in inhibiting cancer cells glycolysis metabolism." (PMID 31612140, 2019). "When microwells were empty in the spiked cancer cell studies (‘blank' wells), the rare-cell scWB did not detect CD45 or GAPDH." (PMID 28332571, 2017). "By contrast, GAPDH or ACTB, which are widely used as RGs are not suitable in this type of cancer as their expression is significantly different in non-photodamaged skin and the different type of NMSC." (PMID 28852586, 2017). "The GAPDH was used as reference gene and its expression level was not significantly (P < .05) different among the untreated control and SMA-treated cancer cell lines examined." (PMID 30460075, 2017). "For the Test Cancer BioChip, the negative controls employed included non-targeting, ACTB, GUSB, GAPDH, RPLP0, TFRC and cyclophilin siRNA as well as no siRNA." (PMID 23049944, 2012). "Though it is not yet known whether GAPDH up-regulation contributes to tumorigenesis sensu stricto, emerging evidence points to the existence of a link between GAPDH up-regulation and the promotion of survival mechanisms in cancer cells as well as chemoresistance." (PMID 22964488, 2012). "We evaluated GAPDH gene expression by real time RT PCR in breast (MCF-7 and T47D) and prostate (PC3 and DU-145) cancer cell lines treated with amino and non-amino bisphosphonates." (PMID 16515701, 2006). "In negative controls, rare-cell scWB analyses of pure WBC populations reported only CD45 and GAPDH signal, with no measurable signal from any cancer-specific protein target, thus establishing co-expression of CD45 and GAPDH, and negative cancer marker response as selective for WBCs." (PMID 28332571, 2017). "However, GAPDH, ACTB, and PPIA have not been included in the census of human cancer genes." (PMID 40943534, 2025). "Interestingly, we observed that GAPDH, GUSB, IPO8, RPL13, RPL32, and UBC genes, as well as RPLP0 + TBP, RPL13 + RPL32, RPL13 + RPLP0, and ACTB + TBP RG pairs, were the only assays whose expression did not depend (P > 0.05) on cancer progression." (PMID 25225161, 2014). "Interestingly, GAPDH and PKM2 are also known for their non-glycolytic roles in cancer, which may also be regulated by O-GlcNAc." (PMID 24918087, 2014).
infection (227 papers, 2005 to 2026). The state of being infected such as from the introduction of a foreign agent such as serum, vaccine, antigenic substance or organism. "We found that when normalized to GAPDH, the infection of A549 cells with PR8 at an MOI of 0.5 and 5.0 caused a significant 40% (P = 0.0001) and 61.3% (P = 0.0001) reduction in HDAC2 mRNA level, respectively." (PMID 28769891, 2017). "As expected, the association of GAPDH mRNA with polysomal ribosomes decreased upon infection from 85 to 40%." (PMID 28074025, 2017). "Fifteen proteins were further selected for elucidating their potential role in virulence, but only disruption of the gene encoding glyceraldehyde-3-phosphate dehydrogenase (GapA) resulted in attenuation of infection in the mouse model." (PMID 29322032, 2017). "Conversely, in susceptible (M-line) snails, GAPDH expression was still detectable after 4 days post-infection and increased throughout the incubation period." (PMID 27015424, 2016). "The protective assays proved that the vaccine constituted by GAPDH is effective against the infections caused by GBS in susceptible and diabetic adult mice." (PMID 26673420, 2015). "GAPDH genes also play a crucial role in plant responses to pathogenic infections." (PMID 40573855, 2025). "We demonstrated that infection with this pathogen may cause humoral response to produce anti-GAPDH antibodies which are cross-reactive with GAPDH sequences of other pathogens and/or healthy gut microflora." (PMID 30224677, 2018). "Likewise, when normalized to GAPDH, the infection with WSN at an MOI of 0.5 and 5.0 caused a significant 40.6% (P = 0.0001) and 60.6% (P = 0.0001) reduction in HDAC2 mRNA level, respectively." (PMID 28769891, 2017). "Notably, not any GAPDH was detected in the nucleus of JEV-infected BHK-21 cells at 36 hpi, suggesting that infection of JEV may cause redistribution of the nucleus-localized portion of GAPDH to the cytosol." (PMID 19368702, 2009). "Differences in metabolic activity were observed between irradiated and infected bees for GaPDH in both experiments and for ATP in Experiment A. Infection alone led to a progressive decline in GaPDH and ATP activity." (PMID 41511945, 2026). "Second, glyceraldehyde-3-phosphate dehydrogenase (GAPDH) plays various physiological roles in infection via secretion in both protozoa and bacteria." (PMID 41551587, 2026). "Infection of human alveolar or bronchial cells with these bacteria triggered the degradation of key cytoskeletal proteins (β-tubulin, β-actin) and cytosolic GAPDH (glycolysis)." (PMID 40639322, 2025). "Research has shown that RPS18 and GAPDH are stably expressed in Apis mellifera after infection with Escherichia coli." (PMID 40266757, 2025). "Following infection with the FilC/PD-1 recombinant vaccinia virus, the table shows, by qPCR and adjusted to GAPDH expression, the relative expression levels of FilC and PD-1 inhibitor genes in several cell lines." (PMID 40988750, 2025). "The up-regulation of glycolytic enzymes, such as PEPCK and GAPDH, reflects metabolic adjustments to meet increased energy demands during infection." (PMID 40152402, 2025). "24h after infection, the viral load and viral protein expression in the blocking groups were significantly reduced (P<0.01), compared with the GAPDH blocking group and control group." (PMID 40642060, 2025). "The expression of luminescence and the quantity of viral RNA in 229E-infected cells exhibited a significant positive correlation (R2 = 0.881, p < 0.0001), normalized to GAPDH 48 h post-infection." (PMID 40241735, 2025). "In our study, GAPDH was found to be relatively stable in the gene quantification analysis on days 18 and 23 post infection with Schistosoma japonicum." (PMID 41156676, 2025). "To illustrate the performance of the COCONUT normalization, we visualized the log2 expression values of commonly used house-keeping genes (ATP6V1B1, and GAPDH) and genes known to be modulated by infection (CEACAM1 and DYSF) as previously shown." (PMID 38817614, 2024).
infection (continued). "This probably sheds light on the infection process, with it requiring at least 48 h post infection to see changes in GAPDH expression." (PMID 38594438, 2024). "mRNA levels of the PEDV ORF3 gene were measured using RT-qPCR and normalized against the host GAPDH gene at different time points post-infection." (PMID 38730463, 2024). "IFNB and CXCL10 gene induction, normalized to GAPDH, were similar after Alpha ΔOrf6 and WT infection, despite lower E RNA levels for Alpha ΔOrf6, consistent with increased innate immune induction by the deletion virus." (PMID 38228858, 2024). "The second candidate, GAPDH was significantly downregulated at 48 h post infection in agreement with the mass spectroscopy data." (PMID 38594438, 2024). "We assessed BMDMs infected with out panel of M. marinum strains for relative levels of transcript abundance for IFN-β, the transcription factor Irf7, and upstream signalling molecule Rig-I relative to the housekeeping gene GAPDH at 8 hours post infection." (PMID 38394154, 2024). "Glyceraldehyde-3-phosphate dehydrogenase (GAPDH), a substrate of caspase-1 during infection or septic shock, is cleaved by YCA1 in a metacaspase-independent manner during H2O2-induced yeast cell death." (PMID 39597678, 2024). "GAPDH has the leading expression stability and correlations to biological processes of infection, as well as anterior segment (with existing animal models), systemic, and neurological ocular diseases through the PCViz & Open Targets Platform." (PMID 38778161, 2024). "To analyze vhs activity in the mutant viruses we conducted quantitative reverse transcriptase real-time PCR using primers for GAPDH and cDNA template prepared from mRNA of cells 6 h post-infection." (PMID 37515256, 2023). "Cell lysates were harvested at 2, 4 and 6 days after infection for western blot analysis of viral nucleocapsid proteins N and GAPDH." (PMID 37197656, 2023). "After normalization to GAPDH using the 2−ΔΔCT method, the results are expressed as a fold change in cytokine gene expression compared to mock infection." (PMID 36883057, 2023). "The infection burden in both assays was quantified by luminescence and qRT-PCR of P. berghei 18S rRNA normalized to host GAPDH." (PMID 37936181, 2023). "CXCL13 and CCL19 mRNAs at these times were then measured by RT-qPCR, and throughout RVFV MP12 infection, relative expression (normalized to GAPDH) of these chemokines continued to increase, suggesting progressive activation of the noncanonical NFκB pathway." (PMID 37515252, 2023). "Under the condition of pathogen infection, the Ct value ranged from a minimum of 19.43 for EF1α to a maximum of 31.82 for GAPDH." (PMID 37761879, 2023). "Among the tobamoviruses, the greatest variation in gene expression was in GAPDH after infection by TMV, TMGMV, ToBRFV and ToMMV." (PMID 36840204, 2023). "For relative quantification, the transcription levels of genes in the MKR-infected host macrophages at 4 hr post-infection were compared with their respective host cells at 0 hr post-infection control and normalized to the GAPDH gene." (PMID 36242542, 2022). "At different times post-infection, cell lysates were prepared and analyzed by Western blotting with antibodies against total TrkA, pTrkA, NP, and GAPDH, respectively." (PMID 36121891, 2022). "Bacterial GAPDH can interact with human hemoglobin and plasminogen to compete for hemin-iron and promote infection in the host cells." (PMID 35414267, 2022). "In this study, after infection, the activity of Rubisco and GAPDH increased in ‘BlackJack’ but the activity in ‘EverGlade’ decreased significantly." (PMID 36319971, 2022). "The densitometry ratio of LC3-II to GAPDH was significantly increased in the ZIKV-infected cells 24 h after the infection, compared with the ratio in the mock-infected cells." (PMID 36405969, 2022).